ENSG00000262526 (novel protein)
Gene: Protein-coding gene on chromosome 17 (7,240,427 to 7,244,635, reverse strand). Ensembl gene ENSG00000262526.
Genetic constraint (gnomAD): Missense variants: 13 observed, 36.39 expected, observed/expected ratio (o/e) 0.36, 90% interval 0.23 to 0.57. Synonymous variants: 17 observed, 13.12 expected, observed/expected ratio (o/e) 1.3, 90% interval 0.88 to 1.83.